ROCK1 (Rho associated coiled-coil containing protein kinase 1)
Diseases named in the same sentence as ROCK1 in open-access papers (continued):
Sharing a sentence is not in itself a finding about the gene and the disease.
breast cancer (continued). "Subsequently, we performed qRT–PCR for verification, and the results showed that after adding GluOC into MDA-MB-231 breast cancer cells, the levels of ROCK1, JAK2, PIK3CA, Bcl-2, CREB were significantly increased, while the expression levels of Bax were significantly decreased." (PMID 39054484, 2024). "Since the discovery of ROCK1 inhibitors, accumulating evidence supports that ROCK1 could be a potential therapeutic target for cancers, including breast cancer, colon cancer and hepatocellular carcinoma." (PMID 35626071, 2022). "TMEM16A and ROCK1/moesin signaling cooperatively promotes breast cancer metastasis." (PMID 35668455, 2022). "ROCK1 activates phosphorylation at T558 to promote the breast cancer metastasis." (PMID 36197602, 2022). "For example, regulation of RhoC/ROCK1/MAPK axis likely alters breast cancer cell progression." (PMID 35179516, 2022). "Overall, our research indicates that MEX3A and RhoA/ROCK1/LIMK signaling may be new targets for breast cancer treatment." (PMID 34486491, 2021). "The increased expression of RhoA or ROCK1 is related to the progression of breast cancer." (PMID 34486491, 2021). "It was also reported that ROCK1 could be targeted by miR‐145 and accelerate cell growth of breast cancer." (PMID 34536977, 2021). "Finally, we assessed the MEX3A dependent regulation of RhoA/ROCK1/LIMK1 signaling pathway involved in the progression of breast cancer." (PMID 34486491, 2021). "ROCK1 activation has been reported to be involved in regulating the mitochondrial translocation of Drp1 and mitochondrial fission through its dephosphorylation at Ser 637 in human breast cancer cells." (PMID 31578315, 2019). "ROCK1 is proved to function as a positive regulator in promoting invasion and metastasis in many types of solid tumors, including bladder, hepatocellular carcinoma, breast cancer and lung cancers." (PMID 31638991, 2019). "Moreover, ROCK1 has been shown to activate proliferation-promoting oncogenes such as c-myc by direct phosphorylation in breast cancer and in prostate cancer." (PMID 31557128, 2019). "Importantly, activated ROCK1 has been found to play a crucial role in regulating mitochondrial fission via the activation of Drp1 in human breast cancer cells." (PMID 31578315, 2019). "In mouse mammary cancer stem cells, ROCK1 inhibition promoted the self-renewal ability." (PMID 27557508, 2016). "Therefore, we treated MDA-MB-231 breast cancer cells with the ROCK1 inhibitor Y-27632 and/or GluOC." (PMID 39054484, 2024). "Therefore, we speculate that MEX3A promotes the progression of breast cancer through RhoA/ROCK1/LIMK signaling pathway." (PMID 34486491, 2021). "In addition, specific ROCK-1 inhibitors, such as Y27632, prevent metastasis in breast cancer." (PMID 34209857, 2021). "Furthermore, MEX3A can regulate RhoA/ROCK1/LIMK signaling pathway in breast cancer cells." (PMID 34486491, 2021). "In addition, we determined that MEX3A could activate RhoA/ROCK1/LIMK1 signaling in the breast cancer cells." (PMID 34486491, 2021). "Therefore, MEX3A modulates the activity of RhoA/ROCK1 signaling in breast cancer." (PMID 34486491, 2021). "Therefore, we investigated whether MEX3A affected RhoA/ROCK1/LIMK1 signaling in breast cancer cells." (PMID 34486491, 2021). "Therefore, we speculated that CNN1 overexpression might inhibit the metastasis of breast cancer by suppressing Rho/ROCK1 pathway." (PMID 31986487, 2020). "In addition, FAM53A may affect the migration and invasion of breast cancer cells by regulating the expression of RhoA, RhoB, RhoC, ROCK1, and MMP9." (PMID 31799197, 2019). "In summary, our in vitro data suggest that GluOC accelerates the metastasis of MDA-MB-231 breast cancer cells by promoting ROCK1/MYPT1/MLC2 signalling, and by promoting breast cancer cell proliferation via the ROCK1/JAK2/PIK3CA/AKT signalling pathway." (PMID 39054484, 2024).
breast cancer (continued). "This study demonstrated that GluOC facilitates the migration of MDA-MB-231 breast cancer cells through the ROCK1/MYPT1/MLC2 signalling pathway and promotes the proliferation of TNBC cells via the ROCK1/JAK2/PIK3CA/AKT signalling pathway." (PMID 39054484, 2024). "Comprehensive KEGG pathway analysis of the DEGs revealed that the ROCK1 and PIK3CA signalling pathways were closely related to the occurrence and development of breast cancer." (PMID 39054484, 2024). "Western blotting further verified that GluOC phosphorylates MYPT1 through ROCK1, which reduces the activity of MYPT1, thereby promoting the phosphorylation of MLC, and ultimately enhancing the migration of MDA-MB-231 breast cancer cells." (PMID 39054484, 2024). "ROCK isoforms differentially regulate the RhoA/ROCK1/p-MLC and RhoA/ROCK2/p-cofilin pathways in a coordinated fashion to modulate breast cancer cell motility in a substrate stiffness-dependent manner through integrin β1-activated FAK signaling." (PMID 37916166, 2023). "LINC01087 is enhanced in breast cancer, and LINC01087 affects ROCK1 expression by sponging miR-335-5p, thereby affecting migration and invasion of breast cells." (PMID 35646642, 2022). "NGF stimulates the invasion of breast cancer MDA-MB-231 cells as a result of the binding of CD44 with the TrkA receptor and the activation of the p115RhoGEF/RhoA/ROCK1 cascade." (PMID 35956937, 2022). "Mechanistically, TEM8 increases active RhoC level and induces ROCK1-mediated phosphorylation of SMAD5, in a cascade essential for promoting stemness and VM capacity of breast cancer cells." (PMID 34285210, 2021). "LINC01087 is enhanced in breast cancer, and LINC01087 affects the expression of ROCK1 by sponging miR-335-5p, thus affecting the migration and invasion of breast cells." (PMID 33968763, 2021). "mRNA and protein expression of ROCK1, ROCK2 and RhoA are increased in the tissue of breast cancer patients; however, only the increased levels of ROCK1 and RhoA correlate with poor patient prognosis." (PMID 27203208, 2016). "The RBP4/RhoA/Rock1 axis has been found to regulate the proliferation, migration, and invasion of ovarian cancer cells, while NRG2 was identified as a prognostic marker for GC and breast cancer and LBP as a prognostic marker for GC." (PMID 40406134, 2025). "Compared with those in the Y-27632 inhibitor group, the P-JAK2 and P-PIK3CA protein levels were significantly increased after the addition of GluOC, and the results showed that ROCK1 regulated JAK2 and PIK3CA, thereby affecting the proliferation and apoptosis of MDA-MB-231 breast cancer cells." (PMID 39054484, 2024). "Likewise, the same effect was seen after specific knockdown of RHOA, ROCK1 and ROCK2 by siRNA in all three ROR2-overexpressing breast cancer cell lines." (PMID 34911552, 2021). "Also, the phosphorylation of RhoA, ROCK1 and LIMK1 in breast cancer cells is positively regulated by MEX3A." (PMID 34486491, 2021). "Besides, the miR-106b-5p mimic enhanced breast cancer canceration by targeting CNN1 and activating Rho/ROCK1 signaling pathway." (PMID 31986487, 2020). "Rho/ROCK1 pathway inhibitor effectively alleviated the role of CNN1 in BRCA cell proliferation and invasion, indicating that miR-106b-5p could promote breast cancer cell cancerization by targeting CNN1 and Rho/ROCK1 pathway." (PMID 31986487, 2020). "Moreover, increasing substrate stiffness may stimulate an integrin β1-activated FAK signaling, which in turn promotes the activation of RhoA/ROCK1/p-MLC and RhoA/ROCK2/p-cofilin signaling cascades toward the motility and migration of breast cancer cells." (PMID 33562737, 2021). "Here, we also demonstrated that RhoA/ROCK1 signaling may play an important role in activation of FAK/Src/paxillin signaling, which was similar to the molecular mechanism of the hypoxia-induced breast cancer cell migration." (PMID 31558699, 2019).
breast cancer (continued). "Furthermore, we found in MDA-MB-231 breast cancer cells that the inhibition of migration is mediated by the GPCR gastrin releasing peptide receptor (GRPR) leading to a reduced expression of migration regulating downstream targets like CDC42 and ROCK1." (PMID 31664083, 2019). "However, in breast cancer, prostate cancer, pancreatic cancer, gastric cancer, as well as in NSCLC cell lines, miR-146a-5p acted as a tumor suppressor through the targeting of Rac1/ROCK1/EGFR." (PMID 27494902, 2016). "More recently, hypoxia-inducible factor (HIF) has been shown to transcriptionally up-regulate RhoA and ROCK1, not but ROCK2, in breast cancer cell lines in response to hypoxia in 2D culture." (PMID 27203208, 2016).
glioma (39 papers, 2013 to 2026). A benign or malignant brain and spinal cord tumor that arises from glial cells (astrocytes, oligodendrocytes, ependymal cells). "In glioma cells, the inhibition of Rho-associated protein kinase 1 (ROCK1) and 2 has been reported to result in differences in cell cycle progression." (PMID 39905470, 2025). "As for the associations of RhoA and ROCK1 with other miRNAs, another study has demonstrated that ROCK1 protein expression was greatly inhibited by miR-145 in the human glioma cell lines, which is in line with our study." (PMID 31541994, 2019). "Rho-associated coiled-coil-containing protein kinase 1 (p-Rock1) is a major regulator of cell invasion/migration in gliomas, Connexin 30 (CX30) is a major means of communication between glioma cells and can contribute to their making a network with normal astrocytes (eventually disrupting it)." (PMID 35148403, 2022). "Furthermore, we have identified that miR-124 regulated the ROCK1 gene, and ROCK1 protein expression caused actin cytoskeleton rearrangements, reduced cell surface ruffle, and suppressed glioma cell invasion." (PMID 23936026, 2013). "Downregulation of ROCK1 in rat glioma cells increased the sensitivity to the anti-neoplastic agent ACNU (nimustin)." (PMID 35328529, 2022). "The miR-124 and miR-145 were both found to target ROCK1 in glioma cells, and inhibit glioma migration." (PMID 35179516, 2022). "The results revealed that knockdown of TROAP drastically downregulated the level of MMP2, MMP7, MMP9, RHOA, RHOA, ROCK1 protein in U251 glioma cell lines compared to control group (p < 0.05)." (PMID 34077623, 2021). "Sevoflurane also attenuated glioma cell proliferation and invasion thorough the upregulation of miR-637 and miR-124, which suppressed the Akt1 expression and ROCK1 signal pathways, respectively." (PMID 33919449, 2021). "We performed rescue experiments to confirm that ROCK1 mediated the effects of LINC00346 on glioma cell growth and invasion." (PMID 32996285, 2020). "Overall, these data revealed that the knockdown of LINC00346 suppressed glioma progression, because of ROCK1 down‐regulation." (PMID 32996285, 2020). "We also showed that an miR‐340‐5p mimic suppressed the proliferation, migration, and invasiveness and promoted the apoptosis of glioma cells, whereas ROCK1 overexpression abrogated these effects of miR‐340‐5p overexpression." (PMID 32996285, 2020). "Sevoflurane exhibits antitumoral properties in glioma cells at least in part by modulation of the miRNA-124-3p/ROCK1 pathway." (PMID 33205044, 2020). "This miRNA function as a potent tumor suppressor by inhibiting vasculogenic mimicry of malignant glioma targeting Rho Associated Coiled-Coil Containing Protein Kinase 1(ROCK1) that disturb hypoxia-induced stress fiber formation and migration of glioma cells." (PMID 33330058, 2020). "We have demonstrated that phosphorylation of ROCK2 instead of ROCK1 was increased in our TMZ-R models of glioma." (PMID 29416017, 2018). "Taken together, these results demonstrate that the miR-584-3p level is positively correlated with the survival time of high-grade (III–IV) glioma patients and that it acts as a prognostic biomarker by targeting ROCK-1." (PMID 26715733, 2016). "Our results have demonstrated a tumor suppressive function of miR-584-3p in glioma, in which it inhibits the migration and invasion of tumor cells by antagonizing hypoxia-induced, ROCK1-dependent stress fiber formation." (PMID 26715733, 2016). "A sufficient concentration of ROCK1-specific small interfering RNAs was transfected into cultured U87 glioma cells, as demonstrated by the knockout efficiency." (PMID 26715733, 2016). "Further immunohistochemical staining of the tissues from the low-grade (I–II) glioma patients also showed that the expression levels of both miR-584-3p and ROCK-1 were low in the low-grade glioma tissues." (PMID 26715733, 2016).
glioma (continued). "Specifically, we have found that ROCK1 is a direct and functionally relevant target of miR-584-3p in glioma cells." (PMID 26715733, 2016). "In malignant glioma, ROCK1 knockdown by shRNA increased the efficacy of nimustine hydrochloride, an alkylating drug used for glioma patients in Japan." (PMID 26725045, 2016). "We also found that the ROCK-1 level was negatively correlated with the survival time of the glioma patients." (PMID 26715733, 2016). "In summary, we have identified RhoGDIα/RhoA/ROCK1 pathway as a regulator of GSCs maintenance, and RhoGDIα is a potential molecular target of GSCs for future therapy of glioma." (PMID 27557508, 2016). "MiR-584-3p expression was strongly negatively correlated with the ROCK-1 level in the tumor tissues from the high-grade (III–IV) glioma patients." (PMID 26715733, 2016). "Further evidence was also obtained by the immunohistochemical staining of 26 human glioma specimens for ROCK-1." (PMID 26715733, 2016). "Further investigation using glioma cell lines and orthotopic implantation of tumors into a nude mouse model revealed that miR-584-3p reduced the migratory and invasive abilities of glioma cells by targeting the hypoxia-induced kinase ROCK1." (PMID 26715733, 2016). "Similar to miR-340, silencing ROCK1 induced glioma cells morphological changes toward mature process of neurocyte." (PMID 25831237, 2015). "miR-124 inhibits glioma cells migration and invasion by down-regulation of ROCK1, a well-known cell mobility-related gene." (PMID 26041995, 2015). "Enforced expression of miR-340 in glioma cells significantly decreased expression of ROCK1 both at protein and mRNA level." (PMID 25831237, 2015). "Results from luciferase reporter assays confirmed that ROCK1 represents a direct target gene of miR-340 in glioma." (PMID 25831237, 2015). "Further investigation revealed that miR-340 suppressed glioma development by directly targeting ROCK1." (PMID 25831237, 2015). "Herein, these results suggested that inhibition of ROCK1 was the key mechanism by which miR-340 suppressed glioma development." (PMID 25831237, 2015). "Our data showed that sh-RNA mediated knock-down of ROCK1 expression promoted morphological change and up-regulated the mature differentiation marker, indicating the new function of ROCK1 deletion inducing glioma cells toward terminal differentiation." (PMID 25831237, 2015). "Selective knockdown of either ROCK1 or ROCK2 exerted antidromic effects on glioma migration: while ROCK1 deletion altered the substrate-dependent migration, deletion of ROCK2 did not." (PMID 24170433, 2014). "To extend these findings to glioma tissues, we also measured ROCK1 mRNA expression by qRT-PCR in the same clinical samples for miR-124 expression." (PMID 23936026, 2013). "Our findings uncovered an important role of miR-124 in glioma morphology, motility and invasion via ROCK1 for the first time." (PMID 23936026, 2013). "All these results were similar to our in vitro observations in miR-124 overexpressioned cells, indicating a potential role of ROCK1 in glioma cell invasion." (PMID 23936026, 2013). "A constitutively active ROCK1 in miR-124 over-expressed glioma cells reversed the effects of miR-124." (PMID 23936026, 2013). "A dual-luciferase reporter assay was used to confirm that miR-124 targeted directly the 3′UTR of ROCK1 gene and repressed the ROCK1 expression in U87MG human glioma cell line." (PMID 23936026, 2013). "Our results revealed a novel mechanism that miR-124 inhibits glioma cells migration and invasion via ROCK1 downregulation." (PMID 23936026, 2013). "Some research groups found that propofol could inhibit the proliferation and invasion of glioma cells by inhibiting the PI3K/Akt-ROCK1 signaling axis." (PMID 35927718, 2022). "Sev could also inhibit glioma cell proliferation and metastasis through the miRNA-124-3p/ROCK1 axis, KCNQ1OT1/miR-146b-5p/STC1 axis, miR-34a-5p/MMP-2 axis, and circ_0002755/miR-628-5p/MAGT1 axis." (PMID 35372041, 2022).